TUBA1B (tubulin alpha 1b)
Diseases named in the same sentence as TUBA1B in open-access papers (continued):
Sharing a sentence is not in itself a finding about the gene and the disease.
esophageal cancer (2 papers, 2024). A primary or metastatic malignant neoplasm involving the esophagus. "Among them, the genes CTSZ, CTSC, DAD, COLEC12, ATOX1, etc., in the TUBA1B+Mac-C0 cluster have a causal relationship with esophageal cancer." (PMID 38434988, 2024). "Through Mendelian randomization of eQTL, it was found that the TUBA1B+Mac-C0 cluster and other cluster have the most maker genes with a causal relationship to esophageal cancer." (PMID 38434988, 2024). "The Mendelian randomization results indicate a causal relationship between genes such as CTSZ, CTSC, DAD1, COLEC12, ATOX1 in the TUBA1B+Mac-C0 cluster and the occurrence of esophageal cancer." (PMID 38434988, 2024).
glioblastoma (2 papers, 2025). The most malignant astrocytic tumor (WHO grade IV). "Based on correlation analyses and immune infiltration assessments, we investigated how TUBA1B affects the immune microenvironment in glioblastoma." (PMID 40094001, 2025).
liver cancer (2 papers, 2017 to 2025). An epithelial or non-epithelial malignant neoplasm that arises from the liver. "TUBA1B expression has been reported to be unregulated in liver tumor tissues, and an increased TUBA1B expression was associated with poor overall survival and resistance to paclitaxel in liver cancer patients." (PMID 28423713, 2017). "Notably, TUBA1B and TTLL4 are the only two genes in this pathway that are highly expressed and associated with poor prognosis in the TCGA liver cancer dataset, with TTLL4 exhibiting a higher hazard ratio than TUBA1B." (PMID 40599993, 2025).
lung adenocarcinoma (2 papers, 2021 to 2025). A carcinoma that arises from the lung and is characterized by the presence of malignant glandular epithelial cells. "The top 30 drugs showing the strongest correlations with TUBA1B expression reinforce its value as a predictive biomarker, while also expanding precision treatment options for lung adenocarcinoma patients." (PMID 39968182, 2025).
lung carcinoma (2 papers, 2012 to 2013). "The down-regulated RPSA, RPL9, TMSB4X and TUBA1B in normal lung (DDD1) were significantly up-regulated in lung cancer (DDD2)." (PMID 23122428, 2012).
mantle cell lymphoma (2 papers, 2020 to 2022). Mantle cell lymphoma is a rare form of malignant non-Hodgkin lymphoma affecting B lymphocytes in the lymph nodes in a region called the ``mantle zone''. "TUBA1B expression was also implicated in the poor prognosis in mantle cell lymphoma." (PMID 32908931, 2020).
Multiple Myeloma (2 papers, 2022). "And then, loss‐of‐function experiments with TUBA1B and TUBB knocked‐down in three myeloma cell lines, which illustrated that TUBA1B and TUBB regulated the levels and activities of a multitude of myeloma cells working on cell cycle, cell proliferation and apoptosis in MM." (PMID 35297204, 2022). "After knocking down TUBA1B gene, cell viability was significantly decreased in myeloma cells, indicating that TUBA1B gene may impact on growth and proliferation of myeloma cell." (PMID 35297204, 2022). "And then, we focus on the TUBA1B and TUBB gene function analysis by knocked‐down in NCI‐H929, RPMI8226 and U266 myeloma cell lines." (PMID 35297204, 2022). "Similarly, we observed that TUBA1B and TUBB regulate the levels and activities of a multitude of myeloma cells working on cell cycle and apoptosis in MM." (PMID 35297204, 2022).
ovarian carcinoma (2 papers, 2012 to 2025). A malignant neoplasm originating from the surface ovarian epithelium. "Similarly, there was a link between the TMSB4X and TUBA1B and the anti-cancer drug resistance to the drug Paclitaxel (PTX) observed in the cervical and breast/ovarian cancers respectively." (PMID 23122428, 2012).
Sepsis (2 papers, 2021 to 2024). Sepsis is defined as life-threatening organ dysfunction caused by a dysregulated host response to infection. "Detection of STMN1+TUBA1B T cells may be able to predict recovery from sepsis." (PMID 38898888, 2024).
Wilms tumor (2 papers, 2020). An embryonal neoplasm characterized by the presence of epithelial, mesenchymal, and blastema components. "We explored the difference in expression of tubulin alpha 1b (TUBA1B) between Wilms' tumor (WT) and normal tissues (NT) from in-house patients and databases, to determine TUBA1B expression in WT and the predictive pathways of coexpressed genes." (PMID 32908931, 2020).
diffuse large B-cell lymphoma (1 paper, 2025). "Our findings reveal a high prevalence of TUBA1B amplifications, with diffuse large B-cell lymphoma showing the highest frequency." (PMID 39968182, 2025).
head-neck cancer (1 paper, 2017). "Co-expression analysis revealed that CAP1 was coexpressed with TUBA1B both in pancreatic and head-neck cancer, as well as with CFL1, CFL2, DSTN, and ROBO1, according to STRING analysis." (PMID 28423713, 2017). "The co-expression analysis revealed that CAP1 was coexpressed with TUBA1B in pancreatic and head-neck cancer, as well as with CFL1, CFL2, DSTN, ACTB, ACTG1, and ROBO1, according to the STRING analysis." (PMID 28423713, 2017). "CAP1 was co-expressed with Tubulin alpha-1B chain (TUBA1B) in both pancreatic and head-neck cancer." (PMID 28423713, 2017).
leukemia (1 paper, 2024). A malignant (clonal) hematologic disorder, involving hematopoietic stem cells and characterized by the presence of primitive or atypical myeloid or lymphoid cells in the bone marrow and the blood. "TUBA1B is situated on human chromosome 12q13.12, and genetic alterations on chromosome 12q have been observed in a broad spectrum of malignancies, including NSCLC, leukemia, and others." (PMID 38589634, 2024).
mental disorder (1 paper, 2023). A disease that has its basis in the disruption of mental process. "Lower levels of TUBA1B were observed in patients with schizophrenia (a serious mental disorder), compared to controls." (PMID 38137937, 2023).
viral hepatitis (1 paper, 2020). An acute or chronic inflammation of the liver parenchyma caused by viruses. "DNA hypomethylation of DCAF4L2, CKLF and UBE2C was observed in both NASH-related and viral hepatitis-related HCCs, whereas that of TRIM4, PRC1 and TUBA1B occurred in a NASH-related HCC-specific manner." (PMID 32685988, 2020).
tumor (28 papers, 2018 to 2025). "Immunological analysis indicates that TUBA1B is linked to cancer-associated fibroblasts and various immune cell infiltrations, implying its involvement in modulating the tumor microenvironment and intercellular communication." (PMID 40094001, 2025). "We noted that TUBA1B overexpression is linked to key immune-related pathways in the tumor immune microenvironment (TIME), such as IL-6/JAK/STAT3 signaling, IL-2/STAT5 signaling, TGF-Beta signaling, and interferon responses." (PMID 39968182, 2025). "These pathways are associated with tumor growth, metastasis, and immune evasion in other cancer types, supporting the multifaceted role of TUBA1B in tumor biology." (PMID 40094001, 2025). "Studies have shown that a protein encoded by a short open reading frame in the TUBA1B gene plays a role in regulating tumor cell proliferation." (PMID 40094001, 2025). "Elevated TUBA1B levels are associated with an immunosuppressive tumor microenvironment, impacting cancer progression and treatment outcomes." (PMID 39968182, 2025). "Results confirmed TUBA1B’s close association with pathways involved in tumor proliferation and immune response." (PMID 39968182, 2025). "To fully understand the genetic mutations affecting TUBA1B, we conducted an analysis of tumor samples from 10,953 patients using the cBioPortal platform." (PMID 39968182, 2025). "Single-cell sequencing analysis indicates that high TUBA1B expression is associated with specific intercellular communications and metabolic pathways, impacting tumor progression." (PMID 40094001, 2025). "TUBA1B's expression impacted some cancers by elevating tumor mutation burden, microsatellite instability, neoantigen formation, immune cell infiltration, and the modulation of immune checkpoints." (PMID 38589634, 2024). "In this present study, we observed a positive correlation between TUBA1B expression and CAFs and MDSCs, both of which are implicated in immune evasion or suppression within the tumor microenvironment." (PMID 38589634, 2024). "Additionally, TUBA1B is engaged in immunomodulation pathways linked to adaptive and innate immunity and cytokine signaling, pointing to its dual involvement in tumor growth and immune system responses." (PMID 39968182, 2025). "Using multi-omics data across 33 different cancer types and advanced analytical techniques such as Gene Set Enrichment Analysis (GSEA) and Gene Set Variation Analysis (GSVA), we clarified TUBA1B’s role in tumor progression and its association with immune pathways." (PMID 39968182, 2025). "Immune data from ImmuCellAI and TIMER2 were analyzed independently, consistently showing a positive correlation between TUBA1B expression and immunosuppressive cells like regulatory T cells (Tregs), tumor-associated macrophages (TAMs), and cancer-associated fibroblasts (CAFs)." (PMID 39968182, 2025). "TUBA1B also demonstrates moderate to high diagnostic accuracy in most tumor types." (PMID 38589634, 2024). "Despite its fundamental roles, TUBA1B’s impact on tumor prognosis and the tumor immune microenvironment across cancer types remains inadequately understood." (PMID 39968182, 2025). "Next, we used the TIDE (Tumor Immune Dysfunction and Exclusion) algorithm to assess the predictive ability of TUBA1B expression for immunotherapy benefits." (PMID 40094001, 2025). "We also conducted in vitro functional assays to assess TUBA1B’s functional role in tumor cells, allowing for a detailed examination of its relationship with cancer prognosis and immune modulation." (PMID 39968182, 2025). "Functional enrichment analyses further revealed that TUBA1B regulates key cell cycle processes, driving tumor proliferation, migration, and invasion." (PMID 39968182, 2025). "In our study, we further utilized IHC staining to assess the protein expression of HRG and TUBA1B in tumor and normal tissues." (PMID 40171266, 2025).
tumor (continued). "The HRG gene was correlated with anti-tumor immune cell infiltration, whereas TUBA1B gene was negatively correlated." (PMID 40171266, 2025). "From six samples, we analyzed single cell sequencing data to understand TUBA1B’s role in the tumor microenvironment." (PMID 40094001, 2025). "Further analysis revealed that TUBA1B upregulation consistently correlated with advanced stages in various cancers, suggesting its role in tumor progression and aggressiveness and its potential as a marker for disease stage." (PMID 39968182, 2025). "This investigation aimed to elucidate the TUBA1B mRNA expression levels across different cancers and compare them between normal and tumor tissues across multiple cancer types." (PMID 39968182, 2025). "To further investigate, we analyzed DNA methylation’s role in TUBA1B expression, given its known impact on immune cell regulation and tumor immunosurveillance." (PMID 39968182, 2025). "Fluorescence imaging results showed that tumor growth was significantly inhibited in the TUBA1B knockdown group." (PMID 40094001, 2025). "To validate the prognostic value of the prognostic genes, we used the IHC stain to detect the protein expression of HRG and TUBA1B in tumor tissues and normal tissues." (PMID 40171266, 2025). "These expression patterns were validated through immunohistochemical data from the Human Protein Atlas (HPA), which showed strong TUBA1B staining in tumor tissues, whereas normal tissues exhibited weaker staining." (PMID 39968182, 2025). "Our research reveals that high TUBA1B expression correlates significantly with decreased tumor purity and increased immune and stromal scores, possibly regulating tumor behavior by influencing immune infiltration." (PMID 40094001, 2025). "This study is the first to explore TUBA1B’s potential in tumor immunity, offering a novel perspective for advancing anti-tumor strategies." (PMID 39968182, 2025). "To deepen understanding of TUBA1B’s role in the immunosuppressive tumor microenvironment, we performed correlation analyses to examine TUBA1B expression, immune cell infiltration, and immune-related gene interactions." (PMID 39968182, 2025). "Our pan-cancer analysis found TUBA1B upregulation across most tumor types, with varying expression patterns in distinct immune and molecular subtypes." (PMID 38589634, 2024). "Using the UALCAN database, we conducted a comparative analysis of TUBA1B promoter methylation levels between normal and tumor tissues." (PMID 38589634, 2024). "Our investigation into the correlation between TUBA1B expression and tumor stages revealed that TUBA1B levels increased with advancing stages in ACC, LIHC, and LUAD, suggesting the potential of TUBA1B as a prognostic marker in these tumors." (PMID 38589634, 2024). "In this study, we conducted a comprehensive pan-carcinoma investigation of TUBA1B to explore its potential as a novel immunotherapy strategy for tumor treatment by assessing its structural characteristics and functions." (PMID 38589634, 2024). "The heat map results showed that in most cancers, TUBA1B expression was negatively correlated with pDC but significantly positively correlated with tumor-promoting Th2 cells." (PMID 38589634, 2024). "Interesting, the ubiquitination at different sites of TUBA1B shows different up- and down-regulation trends in tumor tissues." (PMID 34350460, 2021). "This suggests TUBA1B’s influence on core molecular processes in tumor development." (PMID 39968182, 2025). "The results demonstrated that TUBA1B expression was significantly positively correlated with four tumor stemness indices (DNAss, EREG-METHss, DMPss, and ENHss), while it was significantly negatively correlated with RNAss and EREG.EXPss, all showing statistical significance." (PMID 40094001, 2025). "Targeting TUBA1B may offer promising therapeutic avenues for enhancing cancer treatment, offering new perspectives for innovative anti-tumor strategies with high clinical impact." (PMID 39968182, 2025).
tumor (continued). "Our findings reveal a strong association between elevated TUBA1B expression and an immunosuppressive tumor microenvironment, suggesting TUBA1B may be a predictive marker for immunosuppression within tumors." (PMID 39968182, 2025). "Conversely, TUBA1B expression negatively correlated with immune killer cells, including NK/NKT cells, CD4+ T cells, and CD8+ T cells, which are essential for anti-tumor immunity, indicating that elevated TUBA1B levels may inhibit effective immune responses." (PMID 39968182, 2025). "Finally, we further validated the impact of TUBA1B on tumor progression using a mouse xenograft model." (PMID 40094001, 2025). "Since TUBA1B is highly expressed in these tumors, it is conceivable that TUBA1B might contribute to elevated tumor immune scores and the activation of immune-related genes." (PMID 38589634, 2024). "Furthermore, hypoxia response pathways and Slit/Robo pathway highly associated with angiogenesis, leukocyte chemotaxis and cancer metastasis were significantly upregulated, indicating the pro-tumor potential of TUBA1B+ TAMs." (PMID 39232806, 2024). "Based on these findings, TUBA1B appears to play a role in regulating cancer immunity, and targeting TUBA1B could potentially become a novel strategy for tumor immunotherapy." (PMID 38589634, 2024). "Hence, TUBA1B+ TAMs possessing proliferative and developmental potential also exhibit pro-tumor effects." (PMID 39232806, 2024). "We further investigated the relationship of TUBA1B expression with tumor stage and age." (PMID 35453905, 2022). "Subsequently, our research explored the role of TUBA1B in tumor immunity for the first time." (PMID 35453905, 2022). "In addition, in TCGA colon and rectal cohorts combined cancer data sets, the CCT gene family has a synergistic expression pattern at different stages, whereas the CCT gene family has a similar expression pattern to TUBA1B in normal tissues and tumor tissues." (PMID 34434188, 2021). "When highly expressed in tumor cells, TUBA1B improves their proliferation." (PMID 32211020, 2020). "Moreover, application of μ-155 may suppress pro-inflammatory cytokine production through inhibition of the microtubule component TUBA1B and regulate tumor cell migration through regulation of FLNA (filamin-A)." (PMID 41373892, 2025). "Additionally, we found that TUBA1B exhibited a stronger correlation with tumor-promoting Th2 cells than with antitumor Th1 cells, suggesting a potential skewing of immune responses from antitumor to tumor-promoting in the presence of high TUBA1B expression." (PMID 38589634, 2024). "Hence, we first explored the relationship of TUBA1B with tumor purity and major TIICs." (PMID 35453905, 2022). "Some studies have found that TUBA1B and its homolog TUBA1C are involved in regulating immune cell infiltration within the tumor microenvironment." (PMID 40094001, 2025). "Based on the results of our study, the HRG gene and the TUBA1B gene can predict the prognosis of HCC and accurately respond to the tumor immune microenvironment." (PMID 40171266, 2025). "These overexpressed tumor‐related genes such as tripartite motif‐containing 4 (TRIM4), protein regulator of cytokinesis 1 (PRC1), tubulin alpha 1b (TUBA1B), are closely related to inflammation and malignant differentiation." (PMID 38405061, 2024). "TUBA1B expression also positively correlated with immune-related pathways like interferon-alpha/gamma response, IL-2/STAT5 signaling, and IL6/JAK/STAT3 signaling, indicating TUBA1B’s significant role in the tumor immune microenvironment (TIME)." (PMID 39968182, 2025). "Together, these findings emphasize TUBA1B’s pivotal role in establishing an immunosuppressive TME, offering critical insights for therapeutic strategies aimed at reversing immunosuppression and improving anti-tumor immune responses." (PMID 39968182, 2025).
tumor (continued). "TUBA1C, TUBA1B and the β-tubulin isoform TUBB were found as isoforms with the highest expression levels compared to other isoforms in BC cell lines, and TUBA1C and TUBB were overexpressed in BC tumours compared to the normal breast tissues." (PMID 35167614, 2022). "TUBA1B, an identified survival hazard gene, was underexpressed in NSCLC tumor B cells." (PMID 35804895, 2022). "Furthermore, GSCA was used to examine the role of the TUBA family in tumour-related pathways to distinguish the functions of TUBA1C from those of other members of the TUBA family (TUBA1A and TUBA1B)." (PMID 36466547, 2022). "As result, the α-tubulin isoforms TUBA1B, TUBBA1A and TUBA1C had the highest mRNA expression levels, while TUBA4B and TUBA8 had the lowest expression level among the tubulin isoforms in all the tumor samples." (PMID 30126203, 2018). "In addition, a significant positive correlation between TUBA1B expression and CNV was identified across various cancers, suggesting that CNV may drive TUBA1B dysregulation, influencing tumor progression." (PMID 39968182, 2025). "TUBA1B was overexpressed in NSCLC PBL T cells, C14 CD4/CD8 T cell clusters, and activated tumor Tregs of CD4-C9-CTLA4 (TNFRSF9+) vs. non-activated tumor Tregs of CD4-C9-CTLA4 (TNFRSF9−)." (PMID 35804895, 2022).